HMOX1 (heme oxygenase 1)
Diseases named in the same sentence as HMOX1 in open-access papers (continued):
Sharing a sentence is not in itself a finding about the gene and the disease.
thrombosis (7 papers, 2016 to 2026). "Bone marrow (BM) transplantation from Hmox1−/− donors conferred susceptibility to arterial thrombosis in response to vascular injury to recipient wild type mice." (PMID 35326205, 2022). "Hmox1−/− mice were sensitized to arterial thrombosis and displayed hyperplastic arteries in response to vascular injury." (PMID 35326205, 2022). "More importantly, we observed a significant upregulation of HMOX1 in DVT, and the inhibition of HMOX1 resulted in decreased incidence of thrombosis." (PMID 41467352, 2026). "Collectively, our data elucidate that downregulation of NAT10 mitigates endothelial ferroptosis and prevents DVT formation and progression by modulating HMOX1 expression, which offers a potential novel strategy for the prevention and treatment of thrombosis in DVT." (PMID 41467352, 2026).
abortion (6 papers, 2011 to 2021). the ending of pregnancy by removing a fetus or embryo before it can survive outside the uterus. "Furthermore, the pharmacological inhibition of Hmox1 in pregnant rats resulted in complete fetal resorption, whereas adenoviral overexpression of Hmox1 was shown to sustain pregnancy in abortion-prone mice." (PMID 24503248, 2014).
Arrhythmia (6 papers, 2017 to 2023). Any cardiac rhythm other than the normal sinus rhythm. "In the drug-ingredient-target network of DHI, Akt1 and HMOX1 are the two key gene targets of DHI against arrhythmia." (PMID 35915792, 2022). "Our cell experiments suggested that aconitine could induce arrhythmias and that DHI could rescue the abnormal expression of Akt1 and HMOX1 in aconitine-induced arrhythmias." (PMID 35915792, 2022).
beta thalassemia (6 papers, 2020 to 2025). Beta-thalassemia (BT) is characterized by deficiency (Beta+) or absence (Beta0) of synthesis of the beta globin chains of hemoglobin (Hb). "The production of heme oxygenase 1 (HO-1), a putative regulator of immune function, was increased in beta-thalassemia patients’ blood both with and without Bp stimulation in vitro, highlighting compromised production of IFN-gamma and IL-10 in the blood of patients stimulated with bacteria." (PMID 38892971, 2024). "Importantly, mRNA expression of heme oxygenase 1 (HO-1), a potential modulator of immune function, was increased in whole blood from beta-thalassaemia patients, either with or without stimulation with Bp in vitro." (PMID 32581238, 2020).
cerebrovascular disease (6 papers, 2010 to 2026). "In cerebrovascular disease, the rupture of blood vessels leads to erythrocyte destruction and subsequent hemolysis, releasing hemoglobin, which is further degraded into iron ions, bilirubin, and carbon monoxide by the enzyme heme oxygenase-1 (HO-1)." (PMID 39882361, 2024).
cystic fibrosis (6 papers, 2010 to 2022). Autosomal recessive disorder caused by pathogenic variants in the CFTR gene (cystic fibrosis transmembrane conductance regulator), which encodes a chloride and bicarbonate channel expressed in epithelial cells, and follow the diagnosis criteria. "DNA methylation was associated with pulmonary severity in three genes (HMOX1, GSTM3, and EDNRA) and with a polymorphic deletion that has a protective effect in cystic fibrosis at one gene (GSTM3)." (PMID 28289476, 2017).
falciparum malaria (6 papers, 2010 to 2017). "Other important components of THαβ immune response included up-regulation of HMOX1, FAS, BCL6, TNFRSF10A, and MIP1α were noted in Griffiths’ research, which studied the peripheral blood leukocytes from Kenyan children with acute falciparum malaria." (PMID 24188121, 2013).
glomerular disease (6 papers, 2015 to 2021). "Given that crossing to FVB strain partially rescued the embryonic lethality of Hmox1 deficiency and glomerular disease of transgenic GneM712T/M712T mouse we addressed this question in the presented work." (PMID 25834307, 2015).
Jaundice (6 papers, 2016 to 2025). Yellow pigmentation of the skin due to bilirubin, which in turn is the result of increased bilirubin concentration in the bloodstream. "Previous systematic reviews have identified an association between the HMOX1 promoter and neonatal jaundice." (PMID 37414746, 2024).
membranous nephropathy (6 papers, 2015 to 2023). "Curcumin induced autophagy and alleviated renal oxidative stress through NRF2/HO-1 (Heme oxygenase-1) pathway, which significantly alleviated the development of membranous nephropathy." (PMID 36187470, 2022).
ovarian dysfunction (6 papers, 2019 to 2026). The inability of the ovaries to function. "However, the sustained induction of HMOX1 and the iron overload may paradoxically dysregulate ferroptosis through iron-mediated production of peroxidized lipids, potentially contributing to ovarian dysfunction." (PMID 41262262, 2025).
Salmonella Infections (6 papers, 2013 to 2023). Infections with bacteria of the genus SALMONELLA. "During Salmonella infection, protein expression of HMOX1 increased in the liver of both of A/J and AcB61 mice and in the spleen of AcB61 mice." (PMID 28507548, 2017).
vasculitis (6 papers, 2012 to 2024). "In another case, there was diffuse alveolar hemorrhage reported with suspicion of small vessel vasculitis and yet another case reported HMOX1 deficiency as a mimic of childhood vasculitis outside the lungs." (PMID 33066778, 2020). "Among these, hypoxia-inducible factor-1 (HIF-1), heme oxygenase-1 (HO-1), glucose transporter 1 (GLUT-1), and GLUT-4 stand out as significant protein complexes that promote cardiomyocyte survival and prevent vasculitis, a critical aspect of overall cardiovascular health." (PMID 40376262, 2024).
amnesia (5 papers, 2019 to 2025). Pathologic partial or complete loss of the ability to recall past experiences ( AMNESIA, RETROGRADE) or to form new memories ( AMNESIA, ANTEROGRADE). "In this study, broccoli samples also upregulated the expression of Nrf2 and heme oxygenase-1 (HO-1) in normal BV2 cells and against scopolamine-induced amnesia in mouse brain tissue samples." (PMID 32727144, 2020).
brain inflammation (5 papers, 2012 to 2022). "Similarly, 6–10 weeks of exposure to PM ranging from nanoscale to PM2, 5 in C57BL/6 mice and Wistar rats resulted in increased IL-1α, IL-1β, TNFα, heme oxygenase-1 (HO-1), GFAP, CD14, and CD68 mRNA, which together confirm increased brain inflammation." (PMID 34248501, 2021).
carotid atherosclerosis (5 papers, 2010 to 2025). A thickening and loss of elasticity of the walls of carotid arteries that occur with formation of atherosclerotic plaques. "Based on the results of bioinformatics analysis, we further identified 10 most critical ferroptosis-related genes in carotid atherosclerosis by PPI analysis including HMOX1, IL1B, and NOX4." (PMID 36393970, 2022). "Among them, IL1B and HMOX1 are possible biomarkers or targets of ferroptosis and carotid atherosclerosis." (PMID 36393970, 2022). "In addition, HMOX1 has been identified as a key ferroptosis-related gene in carotid atherosclerosis; however, it has not been thoroughly investigated yet." (PMID 36393970, 2022).
dilated cardiomyopathy (5 papers, 2018 to 2025). Cardiomyopathy which is characterized by dilation and contractile dysfunction of the left and right ventricles. "In mouse models exhibiting dilated cardiomyopathy, the overexpression of heme oxygenase-1 (HO-1) was found to enhance mitochondrial fusion through the upregulation of MFN1 and MFN2 expression levels." (PMID 40661148, 2025).
E. coli infection (5 papers, 2019 to 2025). "Furthermore, to support the effect of NRF2 translocation, NRF2 target genes like HMOX1 were analyzed and found to have decreased mRNA expression in LD4-PP-treated uroepithelial cells but did not alter after E. coli infection." (PMID 41415272, 2025).
fungal keratitis (5 papers, 2017 to 2024). "The authors also revealed that eugenol improves fungal keratitis by activating the nuclear factor erythroid 2-related factor 2/heme oxygenase-1 (Nrf2/HO-1) pathway, which plays an important role in cytokine production." (PMID 39598416, 2024). "In fungal keratitis, HMOX1 can be increased and suppressed levels of antioxidant enzymes, inducing ferroptosis." (PMID 36798084, 2023). "The average ratios of the expression levels of the Hmox1, Nos3, Hif1a, Sod2, Sod3, and Gpx2 genes increased more than 2-fold (p < 0.05) at day 1 p.i. in the fungal keratitis model, whereas the expression ratios of the Hif1an and Prdx6 genes decreased more than 2-fold (p < 0.05)." (PMID 28874754, 2017).
gallbladder cancer (5 papers, 2020 to 2025). "Isoliquiritigenin, a compound extracted from licorice root, induces ferroptosis in gallbladder cancer cells by promoting HMOX1 expression." (PMID 40790027, 2025). "For example, HMOX1 induces ferroptosis by inhibiting GPX4 expression in liver and gallbladder cancer." (PMID 41280724, 2025).
hemochromatosis (5 papers, 2009 to 2025). A disorder of iron metabolism characterized by a triad of HEMOSIDEROSIS; LIVER CIRRHOSIS; and DIABETES MELLITUS. "Genes related to iron regulation, included Hfe, Slc40a1, Hmox1, Tfrc and Gdf15, all of which are directly involved in hemochromatosis and iron overload." (PMID 29257745, 2017). "Three specific iron metabolism genes that have variants known to alter protein function are hemochromatosis (HFE), transferrin (TF), and heme oxygenase-1 (HMOX-1)." (PMID 19165391, 2009). "Because iron can enhance the oxidative effects of lead, we examined whether polymorphisms in iron metabolism genes [hemochromatosis (HFE), transferrin (TF) C2, and heme oxygenase-1 (HMOX-1)] increase susceptibility to the effects of lead on QT interval in 613 community-dwelling older men." (PMID 19165391, 2009).
HIV-1 infection (5 papers, 2014 to 2024). The type species of lentivirus and the etiologic agent of acquired immunodeficiency syndrome (AIDS). "Our study is consistent with their observations, as we observed that HIV-1 infection elevated the expression of heme oxygenase-1." (PMID 38542221, 2024). "For example, a higher expression of genes encoding the chemokine CCL5, heme oxygenase-1 (HMOX-1), thioredoxin reductase, peroxiredoxins, glyceraldehyde-3-phosphate dehydrogenase (GAPDH), etc. are host defense mechanisms well known to negatively regulate HIV-1 infection and replication (77, –, 81)." (PMID 25406321, 2015).
lung mucoepidermoid carcinoma (5 papers, 2014 to 2024). "In mucoepidermoid carcinoma of the lung, HMOX1 overexpression was also associated with the inhibition of cell-cycle progression proteins Cyclin D1 (CCND1) and CCND2, and the stimulated transcription of the cell-cycle arrest proteins Gastrin (GAS) and Cyclin-dependent kinase inhibitor 1C (CDKN1C)." (PMID 31717324, 2019).
medulloblastoma (5 papers, 2020 to 2024). A malignant, invasive embryonal neoplasm arising from the cerebellum. "In medulloblastoma the mechanism of Kv2.1 channel inhibition involves HO-1 (heme oxygenase-1; also known as Hsp32)." (PMID 37175655, 2023). "The importance of KIT signaling for the regulation of HMOX1 expression can also be demonstrated in vitro in 661 W cells, which are derived from a medulloblastoma and whose gene expression profiles suggests a photoreceptor origin." (PMID 32242818, 2020).
periodontal disease (5 papers, 2018 to 2025). "This is evidenced by numerous reports on heme-oxygenase 1 induction in the oral cavity, and is of interest in numerous periodontal diseases." (PMID 37639483, 2023).
pregnancy disorder (5 papers, 2012 to 2022). A disorder that is related to pregnancy. "In pregnancy disorders, such as recurrent miscarriages, intrauterine growth retardation and PE, persistent decreased levels of HMOX1 have been reported." (PMID 31964423, 2020).
rhabdomyosarcoma (5 papers, 2017 to 2021). A rare aggressive malignant mesenchymal neoplasm arising from skeletal muscle. "It was clarified that heme oxygenase-1 (HO-1) suppressed miR-206 levels in rhabdomyosarcoma cells and therefore, treatment with HO-1 inhibitor protoporphyrin IX inhibited cancer cell growth and vascularization through miR-206 elevation." (PMID 29291022, 2017).
skin cancer (5 papers, 2010 to 2023). "In these context, previously we have found that the protein expression levels of Nrf2 and Nrf2-target gene heme-oxygenase-1 (HO-1) were attenuated in the skin tumors of a mouse skin carcinogenesis model." (PMID 20062804, 2010).
status epilepticus (5 papers, 2012 to 2024). Status epilepticus is defined as a continuous seizure lasting more than 30 min, or two or more seizures without full recovery of consciousness between any of them. "Similarly, pilocarpine-induced status epilepticus (SE) strongly induces Nrf2 mRNA and its target genes (heme oxygenase-1 (HO-1), NQO1, and GSTs) in mice." (PMID 32679689, 2020).
triple-negative breast carcinoma (5 papers, 2019 to 2023). An invasive breast carcinoma which is negative for expression of estrogen receptor (ER), progesterone receptor (PR), and human epidermal growth factor receptor 2 (HER2). "Pharmorubicin-induced elevated autophagy and heme oxygenase-1 levels in triple-negative breast cancer cells mediate chemoresistance." (PMID 33809137, 2021).
acute chest syndrome (4 papers, 2014 to 2023). A vaso-occlusive crisis of the pulmonary vasculature occurring in patients with sickle cell disease. "HO-1 induction significantly inhibits markers of tissue inflammation and vaso-occlusion in SCD mice and HMOX1 gene polymorphisms that increase HO-1 expression are associated with reduced incidence of acute chest syndrome in SCD children." (PMID 29694434, 2018). "In SCD patients, individuals with a short GT nucleotide repeat in the hmox-1 gene promoter, hence greater levels of inducible HO-1 protein, had fewer hospitalizations for acute chest syndrome." (PMID 24860503, 2014). "Additionally, polymorphisms in the HMOX1 promoter that correspond to increased HO-1 levels have been correlated with reduced incidents of acute chest syndrome in pediatric SCD patients and overall reductions in vaso-occlusive pain crises and hospitalization rates." (PMID 37144034, 2023).
alcohol (4 papers, 2021 to 2025). "Nrf2 also promotes the production of heme oxygenase-1 (HO-1) to protect hepatocytes from oxidative stress, and HO-1 attenuates alcohol-induced liver damage by suppressing inflammatory responses." (PMID 37891964, 2023).
bone tumors (4 papers, 2013 to 2022). "Among array-identified genes, three (i.e., FABP4, IL-1β, and HMOX-1) were also significantly induced in experimental PC3 bone tumors from HFD mice as compared to LFD mice." (PMID 24240026, 2013). "For example, heme oxygenase 1 (HO-1) was reported to be upregulated in PCa bone tumors but not in subcutaneous tumors of mice with diet induced marrow adiposity, indicating an effect specific to the bone marrow environment." (PMID 35903271, 2022).
brain cancer (4 papers, 2020 to 2025). A primary or metastatic malignant neoplasm affecting the brain. "This is consistent with studies showing that PFKFB4 and HMOX1 are overexpressed in various cancer types and are linked to poorer prognosis and reduced survival rates in brain cancer patients." (PMID 40739397, 2025).
bronchopulmonary dysplasia (4 papers, 2015 to 2023). Bronchopulmonary dysplasia is a chronic respiratory disease that results from complications related to lung injury during the treatment of infant acute respiratory distress syndrome in low-birth-weight premature infants or from abnormal lung development in older infants. "Heme-oxygenase-1 (HMOX1) is an antioxidant defense enzyme for which increased levels were associated with preventing alterations in alveologenesis in bronchopulmonary dysplasia mouse models." (PMID 35415078, 2022).
dementia (4 papers, 2018 to 2025). Loss of intellectual abilities interfering with an individual's social and occupational functions. "Particular focus has been given to the role of heme oxygenase-1 (HO-1)—an important cellular cytoprotectant in preserving mental acuity—using an aging rat model of dementia." (PMID 29662895, 2018).
fetal growth restriction (4 papers, 2012 to 2024). A fetus that does not grow beyond the 10th percentile of conventionally accepted weight for gestational age. "Likewise, the partial deletion of Hmox1 also leads to signs of intrauterine growth restriction." (PMID 32660064, 2020). "Heme Oxygenase-1 (HO-1) has been shown to play a pivotal role in pregnancy outcome and its ablation leads to abnormal placentation, intrauterine fetal growth restriction (IUGR) and subsequent intrauterine fetal death." (PMID 22348450, 2012).
fungal infection (4 papers, 2017 to 2020). "Both bacteria and fungi infected cells induce the expression of heme oxygenase 1, however, our results suggest a more protective effect of human immune cells during fungal infection." (PMID 28797245, 2017). "Fungal infection also increased the mRNA expression and protein production of heme oxygenase-1 (HMOX1) and cyclooxygenase-2 (COX2), with suppressed levels of antioxidant enzymes, superoxide dismutase-1 (SOD1), glutathione peroxidase-1 (GPx1) and peroxiredoxin-4 (PRDX4)." (PMID 28874754, 2017).
hyperhomocysteinemia (4 papers, 2016 to 2022). A serious metabolic condition caused by mutations in the MTHFR gene, medications, or nutritional deficiency. "Previously, hyperhomocysteinemia accelerates AKI to CKD progression by downregulating heme oxygenase-1 (HO-1) expression; consistently, the HO-1 levels were reduced by Hcy treatment in IR mice." (PMID 36551804, 2022).
liver cirrhosis (4 papers, 2012 to 2021). "Our results also suggest that upregulation of HMOX1 may provide better protection of hepatocytes and lead to better clinical outcomes after liver resection in HCC patients with liver cirrhosis." (PMID 29507582, 2018). "Furthermore, upregulation of HMOX1 is worth considering as an effective approach to better protect hepatocytes, which may also lead to better clinical outcomes after liver resection in HCC patients with liver cirrhosis." (PMID 29507582, 2018).
metastatic melanoma (4 papers, 2022 to 2024). A melanoma that has spread from its primary site to another anatomic site. "Following the same pattern, the human metastatic melanoma cores expressed more nuclear HMOX-1 when BRAFV600E was detected in the nucleus." (PMID 35053476, 2022). "This nuclear HMOX-1 expression in nuclear BRAFV600E cores was more prevalent in metastatic malignant melanoma specimens." (PMID 35053476, 2022). "To test our hypothesis that nuclear BRAFV600E enhances HMOX-1 protein expression, we analyzed 30 tissue cores of human cutaneous and metastatic melanomas (15 cores each) for protein expressions of BRAFV600E and HMOX-1 using the IHC technique." (PMID 35053476, 2022).
neonatal jaundice (4 papers, 2020 to 2025). A pigmentation disease characterized by a high level of bilirubin in the blood, causing a yellowing of the skin and other tissues of a newborn infant. "Since HO modulates the heme catabolic pathway and bilirubin production, the functional polymorphisms of HMOX1 are a logical candidate for genetic susceptibility of neonatal jaundice." (PMID 33805292, 2021).
peritonitis (4 papers, 2012 to 2025). Inflammation of the peritoneum (tissue that lines the abdominal wall and covers most of the organs in the abdomen). "In a S. aureus peritonitis model, induction of heme oxygenase-1 following carbon monoxide treatment activated mitochondrial biogenesis in the liver and improved survival." (PMID 36978809, 2023).
renal dysfunction (4 papers, 2012 to 2022). "Similarly, there have been reports on negative effects of sirolimus on IRI (including renal dysfunctions, delayed tubular regeneration and increased expression of heme oxygenase-1), while others observed no negative effect of sirolimus pre-treatment on renal outcome after IRI." (PMID 32625210, 2020).
skin melanoma (4 papers, 2019 to 2022). "Despite therapeutic advancements (e.g. B-RAF inhibitors) targeting cutaneous melanoma, many cellular processes, including inducible heme oxygenase 1 (HO-1), counteract treatments for malignancies." (PMID 30634993, 2019).